CCDC162P (coiled-coil domain containing 162, pseudogene)
Synonyms: bA425D10.7; bA425D10.3; bA487F23.3; C6orf183; C6orf184; C6orf185; CCDC162
Gene: Transcribed unitary pseudogene on chromosome 6 (109,183,955 to 109,355,046, forward strand). Ensembl gene ENSG00000203799.
Diseases named in the same sentence as CCDC162P in open-access papers:
CCDC162P is named in the same sentence as 1 disease in open-access papers, as found by Europe PMC text mining. Sharing a sentence is not in itself a finding about the gene and the disease. The quoted sentences say what the papers report.
breast carcinoma (1 paper, 2020). "Furthermore, the SNP pair ranking fourth map to CDK19 and CCDC162P genes, which are both shown to be affected in breast cancer." (PMID 32957998, 2020).